LRRC4 (leucine rich repeat containing 4)
Diseases named in the same sentence as LRRC4 in open-access papers (continued):
Sharing a sentence is not in itself a finding about the gene and the disease.
glioma (continued). "In addition, we previously unveiled signaling loops involving LRRC4, AP-2, miR-182, and LRRC4 (the LRRC4-AP-2-miR-182-LRRC4 loop) and LRRC4, miR-185, SP1, DNMT1, and LRRC4 (the LRRC4-miR-185/SP1-DNMT1-LRRC4 loop), which play important role in glioma." (PMID 32117780, 2020). "MiR-381 regulates LRRC4, leading to upregulation of the MEK/ERK and AKT signaling and enhanced the PI3-K/AKT signaling pathway activity, in turn resulting in increased proliferation of glioma cells." (PMID 33324542, 2020). "Thus, the expression of LRRC4 is likely to have significant potential as a therapeutic marker and target for TMZ treatment in glioma patients." (PMID 32372061, 2020). "Furthermore, the levels of LRRC4, DEPTOR and autophagy are clinically relevant for GBM, indicating that LRRC4 is likely to have significant potential as a therapeutic marker and target for TMZ treatment in glioma patients." (PMID 32372061, 2020). "The methylation-mediated LRRC4 inactivation is a frequent event in astrocytoma, and we found that the LRRC4 promoter was methylated in all glioma cell lines and primary gliomas but not in normal brain tissue." (PMID 29312296, 2017). "LRRC4/NGL-2 is a target gene of some miRNAs (such as miR-182 and miR-381); meanwhile, it is capable of regulating miRNAs as a tumor suppressor and forms multiphase loops with miRNAs, transcription factors and gene methylation modification in glioma." (PMID 25526788, 2014). "Therefore, the LRRC4/NGL-2-SP1-DNMT1-LRRC4/NGL-2 loop formed among LRRC4/NGL-2, SP1 and DNMT1 took part in the glioma formation." (PMID 25526788, 2014). "ISH analysis of miR-182 and miR-381 and IHC analysis of BRD7 and LRRC4 showed that all 47 primary gliomas had elevated levels of miR-182, miR-381, and BRD7 (except for one case), and decreased levels of LRRC4 (except for two cases), as compared to levels detected in the 21 normal brain tissues." (PMID 24404152, 2014). "LRRC4/NGL-2 was found to be predominantly expressed in the normal brain tissues, though it was deleted or down-regulated in primary brain tumor biopsies (up to 87.5% in gliomas, 80.9% in meningiomas and 85.2% in pituitary and other brain tumors)." (PMID 25526788, 2014). "No known studies have found genetic alterations in the LRRC4 coding sequence in glioma biopsies or cell lines." (PMID 18976507, 2008). "Our previous study showed that the expression of LRRC4 was absent in glioma cell lines SF126 and SF767." (PMID 18976507, 2008). "Combined LRRC4 expression and TMZ treatment could be an effective strategy for glioma therapy." (PMID 32372061, 2020). "However, the molecular mechanism by which LRRC4 regulates glioma tumorigenesis has not been fully elucidated." (PMID 24404152, 2014). "In addition, LRRC4/NGL-2 might be a negative regulator of the RPTP-zeta receptor, contributing to the suppression of the invasion ability of glioma cells." (PMID 25526788, 2014). "Since LRRC4 promoter methylation is found in glioma but not in the normal brain, it may distinguish tumors from normal tissue and serve as a promising biomarker for diagnosis." (PMID 18976507, 2008). "Furthermore, LRRC4 promoter methylation was observed by methylation-specific PCR in two glioma cell lines and all 30 primary glioma specimens, but not in normal brain tissue." (PMID 18976507, 2008). "In addition, the methylase inhibitor 5-Aza-2'-deoxycytidine could induce LRRC4 mRNA expression and LRRC4 promoter partial demethylation in SF126 and SF767 glioma cells." (PMID 18976507, 2008). "Furthermore, the methylation of LRRC4/NGL-2 was detected in both the early and late stages of glioma, indicating that the inactivation of the LRRC4/NGL-2 gene might be essential in the early development of glioma and persist through the course of development." (PMID 25526788, 2014). "However, no genetic alterations of the LRRC4/NGL-2 coding region were found in glioma." (PMID 25526788, 2014).
glioma (continued). "LRRC4 is primarily expressed in normal brain tissues whilst lacking in GBM cells and primary glioma cells." (PMID 32372061, 2020). "LRRC4 also is a tumor suppressor gene, and it is decreased in World Health Organization (WHO) grades II and III gliomas and absent in glioblastoma (WHO, grade IV)." (PMID 27884160, 2016). "LRRC4/NGL-2 was highly specific in brain tissue and grade I gliomas (WHO), but it was reduced or absent in grade II-III gliomas and absent in glioblastoma (WHO, grade IV)." (PMID 25526788, 2014). "Here, the LRRC4 promoter was found to be methylated in two glioma cell lines (SF126 and SF767) and all 30 primary gliomas that we have collected, but not in the normal brain tissue samples, suggesting that LRRC4 methylation is a tumor-specific event." (PMID 18976507, 2008).
glioblastoma (13 papers, 2010 to 2023). The most malignant astrocytic tumor (WHO grade IV). "LRRC4 has been verified to be a hypermethylated gene and loss expression in glioblastoma." (PMID 29312296, 2017). "LRRC4 can also act as a tumor suppressor gene to significantly inhibit glioblastoma cell proliferation by interacting with extracellular and intracellular signaling pathways." (PMID 36649279, 2023). "For instance, miR-381-3p overexpression promotes cancer cell proliferation in glioblastoma cells and osteosarcoma cells by targeting the brain relative specific expression gene LRRC4." (PMID 32411707, 2020). "In glioblastoma cells, ectopic LRRC4 expression competitively inhibited the interaction of endogenous mitogen-activated protein kinase (MEK) and ERK1/2." (PMID 27884160, 2016). "Our results indicated that enforced LRRC4 expression prevents the activation of ERK downstream transcription factors to inhibit glioblastoma cell proliferation and invasion." (PMID 27884160, 2016). "Ectopic LRRC4 expression inhibited glioblastoma cell proliferation and invasion in an ERK-dependent manner." (PMID 27884160, 2016). "Introduction of LRRC4 into glioblastoma cells reduced CXCR4 expression, CXCL12-induced ERK and AKT phosphorylation and matrix metalloproteinase expression." (PMID 20376365, 2010). "LRRC4 is a tumor suppressor gene in glioblastoma, apparently regulating ERK/AKT/NF-kB signaling." (PMID 27633254, 2016). "Moreover, LRRC4/NGL-2 inhibits glioblastoma cell proliferation, migration and angiogenesis by downregulating pleiotropic cytokine expression and response." (PMID 25526788, 2014). "LRRC4 deletion contributes to glioblastoma multiforme (GBM) malignant progression, while LRRC4 overexpression inhibits GBM cell proliferation and invasion by inhibiting the RTK/ERK/AKT/NF-kB signaling pathway." (PMID 32117780, 2020). "Decreasing or silencing LRRC4 reduced its ability to inhibit the activation of ERK1/2 and nuclear translocation and then promoted tumorigenesis and progression of glioblastoma." (PMID 27884160, 2016). "Enforced expression of LRRC4 reduced the activity of the Ras/c-Raf/ERK/MAPK and PI-3 K/AKT signaling pathways and inhibited cell proliferation and invasion in glioblastoma cells." (PMID 27884160, 2016). "The absence of LRRC4 expression contributes to late events in the pathogenesis of malignant glioblastoma." (PMID 27884160, 2016).
astrocytomas (3 papers, 2014 to 2017). "In contrast, the expression of LRRC4 in astrocytomas gradually decreased with increase in WHO grade, from I to III, and was completely absent in grade IV astrocytomas." (PMID 24404152, 2014). "More importantly, we also found that miR-182, miR-381 and BRD7 were inversely correlated with LRRC4 in astrocytomas of various pathological grades, and the extent of correlation increased from WHO grade I to IV." (PMID 24404152, 2014). "The interactions between miR-381/miR182 and LRRC4/NGL-2 were identified to be involved in the pathological progression of astrocytoma." (PMID 25526788, 2014). "In addition, we found that LRRC4 expression was closely correlated with the prognosis of astrocytoma patients, with high expression of LRRC4 suggesting a good prognosis." (PMID 29312296, 2017). "We also showed that Treg cell infiltration in the tumor microenvironment increased with the astrocytomas grade and that almost all Ti-Treg cells expressed the CCR4 receptor, whereas LRRC4 expression showed a negative correction with Ti-Treg cells in GBM." (PMID 29312296, 2017). "LRRC4 is decreased in WHO grades II and III astrocytomas and is consistently absent in GBM." (PMID 29312296, 2017).
brain tumor (3 papers, 2014 to 2016). "LRRC4/NGL-2 displays down-regulation or expression deletion in primary brain tumor biopsies and has the potential to suppress brain tumor growth." (PMID 25526788, 2014).
rosacea (3 papers, 2023 to 2026). A chronic erythematous skin disorder that affects the face. "Most importantly, our results demonstrated that in an LL37-induced rosacea mouse model, mutation in Lrrc4 facilitates rosacea-like skin inflammation by neuropeptide VIP derived from peripheral neurons." (PMID 37402769, 2023). "In a mouse model recapitulating a recurrent Lrrc4 mutation from human patients, we find rosacea-like skin inflammation, underpinned by excessive vasoactive intestinal peptide (VIP) release by peripheral neurons." (PMID 37402769, 2023). "In the present study, based on WGS of 3 large rosacea families (as discovery cohort) and WES of 49 additional small rosacea families (as validation cohort), we identified LRRC4, SH3PXD2A, and SLC26A8, each with a single rare genetic variant, as potential candidate genes for rosacea susceptibility." (PMID 37402769, 2023). "By utilizing an antagonist peptide of VIP receptor, VIPhyb34,35, we found that inhibition of VIP signaling could greatly improve rosacea-like dermatitis in Lrrc4 mutant mice compared with the mice treated with scrambled VIPhyp peptides (sVIPhyp)." (PMID 37402769, 2023). "Furthermore, through whole‐genome sequencing, researchers identified three genes—LRRC4, SH3PXD2A, and SLC26A8—each of which has rare genetic variations associated with susceptibility to rosacea within families, indicating these genes as potential susceptibility genes." (PMID 41437844, 2026).
autism spectrum disorder (2 papers, 2021 to 2025). A spectrum of developmental disorders that includes autism, and Asperger syndrome. "In addition, Leucine-rich repeat-containing protein 4 (LRRC4) is a key protein that regulates the formation of excitatory synapses and promotes axon differentiation, and mutations in LRRC4 can lead to CNS diseases such as autism spectrum disorder." (PMID 41012511, 2025). "Mutations in LRRC4 occur in Autism Spectrum Disorder (ASD) and intellectual disability." (PMID 33932995, 2021). "Moreover, mutations of LRRC4 gene in humans have been implicated in Autism Spectrum Disorder (ASD), and intellectual disability." (PMID 33932995, 2021).
epithelial ovarian cancer (2 papers, 2020 to 2021). "In ovarian cancer orthotopic xenograft, LRRC4 overexpression inhibits metastasis of ovarian cancer cells." (PMID 32117780, 2020). "Although EMT and MET are methods of tumor metastasis in ovarian cancer patients, our current study shows that LRRC4 acts as a suppressor gene to inhibit EOC cell collective invasion in an E-cadherin-dependent manner but not through EMT." (PMID 32117780, 2020). "Furthermore, E-cadherin expression was present in the ascites of ovarian cancer patients and was accompanied by low LRRC4 expression." (PMID 32117780, 2020). "At the mechanistic level, we showed that LRRC4 binds to the c-SH2 domain of PIK3R1 to inhibit the activity of PIK3R1 and subsequently disrupts E-cadherin-dependent collective invasion of ovarian cancer cells mediated by the PIK3R1 signaling pathway." (PMID 32117780, 2020).
experimental autoimmune encephalomyelitis (2 papers, 2021 to 2025). An autoimmune demyelinating disease of the central nervous system that is produced experimentally in animals by the injection of homogenized brain or spinal cord in Freund's adjuvant. "LRRC4 regulates the formation of excitatory synapses and promotes axon differentiation, and it has been reported to promote a neuroprotective effect in experimental autoimmune encephalomyelitis." (PMID 40727427, 2025). "LRRC4 was detected in the CNS of experimental autoimmune encephalomyelitis (EAE) mice by the use of real-time PCR and western blotting." (PMID 33932995, 2021).
malignant glioma (2 papers, 2008 to 2014). A grade III or grade IV glioma arising from the central nervous system. "More importantly, LRRC4 had the potential to suppress tumorigenesis of U251 malignant glioma cells in vivo and cell proliferation in vitro." (PMID 18976507, 2008). "LRRC4/NGL-2 was a candidate tumor suppressor gene that may be involved in the pathogenesis of malignant glioma." (PMID 25526788, 2014). "Our previous studies demonstrated that the expression of the LRRC4 gene was not only highly specific in brain tissue, but also a candidate tumor-suppressor gene that may be involved in the pathogenesis of malignant gliomas." (PMID 18976507, 2008). "It was found to be predominantly expressed in normal brain tissue and involved in early nervous system development and differentiation, but the expression of LRRC4 was absent in several malignant glioma cell lines." (PMID 18976507, 2008).
pituitary adenoma (2 papers, 2014 to 2021). "Furthermore, LRRC4/NGL-2 is downregulated expression in pituitary adenoma, polymorphisms or haplotypes in the LRRC4/NGL-2 and may have important research significance by predicting the risk of pituitary adenoma." (PMID 25526788, 2014).
adenoma (1 paper, 2021). A neoplasm arising from the epithelium. "These authors found that OPLAH alone and/or a combination of a few methylated DNA markers (ARHGEF4, LRRC4, ANTXR1, PITX1) can discriminate adenomas and CRC in LS patients." (PMID 34201893, 2021).
amyotrophic lateral sclerosis (1 paper, 2021). Amyotrophic lateral sclerosis (ALS) is a neurodegenerative disease characterized by progressive muscular paralysis reflecting degeneration of motor neurons in the primary motor cortex, corticospinal tracts, brainstem and spinal cord. "RNA sequence analysis also showed that Rab7b expression was the elevated gene in mice with LRRC4 deletion involving amyotrophic lateral sclerosis." (PMID 33932995, 2021).
Autoimmunity (1 paper, 2021). The occurrence of an immune reaction against the organism's own cells or tissues. "Thus, LRRC4 ectopic expression alleviates the defects in demyelination and autoimmunity caused by EAE." (PMID 33932995, 2021).
colon cancer (1 paper, 2021). "Combined with our results, we have more reason to believe that LRRC4C is involved in the tumour progression of colon cancer and gastric cancer in a similar way to LRRC4." (PMID 33867855, 2021).
encephalomyelitis (1 paper, 2025). Inflammation of the brain and the spinal cord. "(2021) by using a murine model of encephalomyelitis (EAE), identified that the proteins encoded by LRRC4 gene have a neuroprotective role." (PMID 40421009, 2025).
ovarian insufficiency (1 paper, 2025). "Progressive loss of fertility is considered the most intuitive result of ovarian insufficiency; hence, we first evaluated the fertility of wild‐type (WT) and Lrrc4−/− mice." (PMID 40317712, 2025). "To determine whether LRRC4 treatment can alleviate ovarian insufficiency, we established a POI‐like mouse model by CTX and reinforced LRRC4 via the intraperitoneal injection of adeno‐associated virus (AAV)–LRRC4." (PMID 40317712, 2025).
ovarian serous cystadenocarcinoma (1 paper, 2020). A malignant serous cystic epithelial neoplasm arising from the ovary. "We first conducted genomic analyses of 489 human ovarian serous cystadenocarcinomas using the Cancer Genomics Atlas (TCGA), which revealed an inverse relationship between LRRC4 and PIK3R1 expression." (PMID 32117780, 2020).
serous cystoma (1 paper, 2020). "We next examined LRRC4 expression in 8 serous cystoma, 30 primary HGSC, and 19 omental metastasis samples by using immunochemistry (IHC), verifying that LRRC4 was significantly down-regulated in primary HGSC (p < 0.05) and omental metastasis samples (p < 0.01) compared with serous cystoma samples." (PMID 32117780, 2020).
serous ovarian cancer (1 paper, 2020). "LRRC4 expression was also reduced in serous ovarian cancer cells with ascitic cytology-positive patients, suggesting that low expression of LRRC4 is associated with high-degree EOC malignant progression and metastasis." (PMID 32117780, 2020). "We first examined the expression of LRRC4 in 5 normal ovarian tissues, 11 low-grade serous ovarian cancer (LGSC), 8 low malignant serous ovarian cancer (LMSC), and 17 HGSC samples using Gene Expression Omnibus (GEO) databases." (PMID 32117780, 2020). "Analysis of the open database and experiments with immunochemistry showed that LRRC4 is lowly expressed in high-grade serous ovarian cancer (HGSC) cells and during EOC metastasis." (PMID 32117780, 2020).